KDM6B (lysine demethylase 6B)
Description:
Histone demethylase that specifically demethylates 'Lys-27' of histone H3, thereby playing a central role in histone code. Demethylates trimethylated and dimethylated H3 'Lys-27'. Plays a central role in regulation of posterior development, by regulating HOX gene expression. Involved in inflammatory response by participating in macrophage differentiation in case of inflammation by regulating gene expression and macrophage differentiation. Plays a demethylase-independent role in chromatin remodeling to regulate T-box family member-dependent gene expression by acting as a link between T-box factors and the SMARCA4-containing SWI/SNF remodeling complex (By similarity).
Synonyms: JMJD3; KIAA0346; NEDCFSA; NEDSST
Tractability: Small molecule: a structure with a bound ligand is known; a high-quality ligand is known. PROTAC: UniProt records ubiquitination sites on it; ubiquitination databases record sites on it; a small molecule that binds it is known.
Target class: Epigenetic regulator; Jumonji domain-containing; Eraser; Lysine demethylase
Chemical probes: GSK-J1, GSK-J4 (high quality), IOX1 (high quality)
Gene: Protein-coding gene on chromosome 17 (7,834,193 to 7,854,796, forward strand). Ensembl gene ENSG00000132510.
Subcellular location: Nucleus
Subcellular location (Human Protein Atlas): Nuclear speckles
Pathways (Reactome):
Cellular responses to stimuli: Oxidative Stress Induced Senescence
Chromatin organization: HDMs demethylate histones
Developmental Biology: Chromatin modifications during the maternal to zygotic transition (MZT)
Gene Ontology:
Molecular function: histone H3K27me2/H3K27me3 demethylase activity; protein binding; chromatin DNA binding; histone demethylase activity; RNA polymerase II cis-regulatory region sequence-specific DNA binding; beta-catenin binding; chromatin binding; histone H3 methyltransferase activity; sequence-specific DNA binding
Biological process: cardiac muscle cell differentiation; chromatin remodeling; endothelial cell differentiation; heart development; mesodermal cell differentiation; positive regulation of cold-induced thermogenesis; positive regulation of transcription by RNA polymerase II; regulation of gene expression; hippocampus development; inflammatory response to antigenic stimulus; response to activity; response to fungicide
Cellular component: MLL3/4 complex; nucleoplasm; nucleus
Genetic constraint (gnomAD): Loss-of-function variants: 21 observed, 143.04 expected, observed/expected ratio (o/e) 0.15, 90% interval 0.1 to 0.21. The synonymous counts are far from expectation, so gnomAD's model fits this gene poorly and the ratio says little. Missense variants: 1,981 observed, 2,217.4 expected, observed/expected ratio (o/e) 0.89, 90% interval 0.86 to 0.93. Synonymous variants: 1,143 observed, 915.61 expected, observed/expected ratio (o/e) 1.25, 90% interval 1.19 to 1.31.
Gene-disease validity (ClinGen):
ClinGen rates the evidence that KDM6B causes each of these diseases.
syndromic intellectual disability (autosomal dominant): Definitive. A intellectual disability that is part of a larger syndrome.
syndromic intellectual disability (autosomal recessive): Limited.
Homologues: Orthologues: chimpanzee KDM6B (99% identical), macaque KDM6B (98% identical), pig KDM6B (95% identical), dog KDM6B (94% identical), mouse Kdm6b (92% identical), rat Kdm6b (92% identical), rabbit KDM6B (90% identical), guinea pig KDM6B (77% identical), tropical clawed frog kdm6b (47% identical), zebrafish kdm6ba (43% identical), zebrafish kdm6bb (34% identical), Drosophila melanogaster Utx (21% identical), and 4 more. Paralogues in human: KDM6A (28% identical), UTY (27% identical).
Diseases named in the same sentence as KDM6B in open-access papers:
KDM6B is named in the same sentence as 225 diseases in open-access papers, as found by Europe PMC text mining. Sharing a sentence is not in itself a finding about the gene and the disease. The quoted sentences say what the papers report.
breast carcinoma (51 papers, 2014 to 2026). "We identified the co-occurrence of the EEF1AKNMT::DNM3 (ED) fusion and KDM6B deletion as a novel prognostic biomarker associated with aggressive tumor biology and reduced survival in luminal breast cancer." (PMID 42302066, 2026). "KDM6B, which is upregulated in luminal breast cancer, was significantly associated with the upregulation of EMT signals and poor clinical prognosis." (PMID 35453496, 2022). "It was found that KDM6B can inhibit breast cancer metastasis by regulating the Wnt/β-linked protein signaling pathway; while in ovarian cancer, KDM6B promotes cancer cell migration and invasion by inducing the expression of transforming growth factor β1." (PMID 36564369, 2022). "Here, we show that KDM6B is significantly down‐regulated in human breast cancer tissues, and its low expression is associated with poor prognosis of patients with breast cancer." (PMID 34165914, 2021). "In this study, we verified that KDM6B was down‐regulated in human breast cancer tissues, and low KDM6B expression was associated with poor prognosis of patients with breast cancer." (PMID 34165914, 2021). "Moreover, the elevated levels of miR-138-5p in the serum exosomes of breast cancer patients were positively associated with later stages, while the tissue expression of its target, KDM6B, was significantly lower in cancer patients than in normal controls." (PMID 36012638, 2022). "Breast cancer-derived exosomal miR-138-5p downregulates KDM6B expression in macrophages, which results in the polarization of macrophages towards the M2 type and the reduction of KDM6B recruitment to the promoters of M1-related genes." (PMID 40612677, 2025). "miR-138-5p was transferred from breast cancer to TAMs via exosomes, downregulating the expression of KDM6B, suppressing M1 polarization, and promoting M2 polarization." (PMID 40443670, 2025). "They determined that ex-miR-138-5p stimulates lung metastasis of breast cancer cells by suppressing the expression of KDM6B in macrophages, and the level of circulating ex-miR-138-5p was found to be positively correlated with the progression of breast cancer." (PMID 39432619, 2024). "The 3’-untranslated region of KDM6B was the target of increased production of miR-138-5p in EVs in breast cancer cell-derived EVs, which promoted M2 polarization by inhibiting the expression of KDM6B in macrophages." (PMID 38690261, 2024). "Breast cancer cells can downregulate the expression of epigenetic factor lysine demethylase 6B (KDM6B) in TAMs by delivering miR-138-5p via exosomes to TAMs." (PMID 36624542, 2023). "miR-138-5p prevented M1 polarization and promoted M2 differentiation of macrophages by inhibiting the expression of KDM6B in macrophages, and significantly promoted lung metastasis of breast cancer in mice." (PMID 37901333, 2023). "In patients, low expression of menin favors tumorigenesis and reduced levels of KDM6B favor the metastasis of breast cancer cells." (PMID 37367050, 2023). "In metastatic melanoma and breast cancer samples, a significantly high positive correlation was observed between KDM6B and HIF1α mRNA (R = 0.45, p-value = 0.018; R = 0.26, p-value = 0.0014)." (PMID 35186918, 2022). "KDM6B overexpression was also shown to inhibit the proliferation, colony-forming ability and migratory capacity of breast cancer cells in vitro." (PMID 35915507, 2022). "Breast cancer cells acquire drug resistance to PI3K inhibitor via upregulation of KDM6B-mediated IGFBP5 expression." (PMID 34950587, 2021). "In this study, our data provided evidence that KDM6B expression decreased significantly in breast cancer tissues compared with normal tissues, which confirmed our TCGA dataset analysis." (PMID 34165914, 2021). "In this study, we found that KDM6B expression was negatively correlated with β‐catenin expression in breast cancer using TCGA dataset analysis." (PMID 34165914, 2021).
breast carcinoma (continued). "In our study, high expression of KDM6B inhibited EMT of breast cancer cells, which was confirmed in the xenografts." (PMID 34165914, 2021). "Here, we first examined the effect of MB-MDA-231 breast cancer cells on KDM6B expression in the macrophage-like cell line THP-1." (PMID 34093857, 2021). "Here we present evidence for the downregulation of KDM6B expression in macrophages cocultured with miR-138-5p-enriching breast cancer cells." (PMID 34093857, 2021). "Our findings collectively support that KDM6B overexpression inhibits the migration and metastasis of breast cancer cells in vitro." (PMID 34165914, 2021). "CCK‐8 and colony formation assays were performed to explore the effect of KDM6B on the proliferation of breast cancer cells." (PMID 34165914, 2021). "All these data suggested that overexpression of KDM6B inhibited proliferation, migration and metastasis of breast cancer cells probably regulating the Wnt/β‐catenin signaling pathway." (PMID 34165914, 2021). "We investigated the effect of histone demethylase lysine‐specific demethylase 6B (KDM6B) on metastasis of breast cancer." (PMID 34165914, 2021). "Our previous study also showed that KDM6B inhibited the stem cell‐like properties of breast cancer by inhibiting the expression of OCT4." (PMID 34165914, 2021). "The results showed that KDM6B expression was significantly reduced in breast cancer compared with normal subjects." (PMID 34165914, 2021). "Here, we show that miR-138-5p produced by breast cancer cells was transferred to macrophages via exosomes, resulting in the inhibition of KDM6B expression and activity." (PMID 34093857, 2021). "The results showed that the expression of KDM6B was negatively correlated with that of KI67 in breast cancer." (PMID 34165914, 2021). "Our findings implied a novel molecular mechanism that overexpression of KDM6B inhibited metastasis of breast cancer cells probably by regulating the Wnt/β‐catenin signaling pathway." (PMID 34165914, 2021). "Our previous study showed that KDM6B inhibited the stem cell‐like properties of breast cancer by inhibiting the expression of stemness‐related transcription factor OCT4." (PMID 34165914, 2021). "Epigenetic regulation is required for the differentiation and functional programming of macrophages 6, 30, leading us to investigate the role of the H3K27 histone demethylase KDM6B in the progression of breast cancer." (PMID 34093857, 2021). "We found that KDM6B‐overexpressing MDA‐MB‐231 breast cancer cells grew significantly smaller in terms of volume and weight than the controls." (PMID 34165914, 2021). "We further found that miRNA-138-5p mediated the inhibition of KDM6B expression and that the transfer of exosomal miRNA-138-5p, produced by human breast cancer cells, to macrophages inhibited the expression of KDM6B." (PMID 34093857, 2021). "Consistently, real‐time quantitative PCR and western blotting assays in five breast cancer cell lines indicated that a sharp decrease in KDM6B mRNA and protein levels occurred compared with mammary MCF10A cells." (PMID 34165914, 2021). "To test the carcinogenic activity of KDM6B in breast cancer, we analyzed the relationship between the expression of KDM6B and KI67 using TCGA dataset." (PMID 34165914, 2021). "Overall, our findings provide novel insights into suppression of metastasis of breast cancer cells by KDM6B via β‐catenin and suggest involvement of the KDM6B‐Wnt/β‐catenin axis in breast cancer progression." (PMID 34165914, 2021). "Taken together, our results provided the support that KDM6B was lowly expressed in breast cancer, and the low‐level expression of KDM6B was closely associated with poor prognosis of patients with breast cancer." (PMID 34165914, 2021). "In recent studies on breast cancer, it has been found that miR-138-5p mimics can be transfected to up-regulate miR-138-5p which reduced the expression of KDM6B and thus inhibited M1 polarization and promoted M2 polarization of macrophages in breast cancer." (PMID 34660700, 2021).
breast carcinoma (continued). "Reports have shown that KDM6B has increased expression or abnormal activity in prostate cancer, breast cancer, kidney cancer, and other tumors, and plays a carcinogenic role." (PMID 34001062, 2021). "The results showed that the expression of KDM6B was negatively correlated with that of β‐catenin in breast cancer." (PMID 34165914, 2021). "More importantly, Kaplan–Meier analysis suggested that the overall survival rate of patients with breast cancer with low KDM6B expression was poorer than that of patients with high KDM6B expression." (PMID 34165914, 2021). "Our findings suggest that KDM6B inhibits the metastasis of breast cancer probably by regulating Wnt/β‐catenin signaling, which provides a novel mechanistic role of KDM6B in breast cancer metastasis." (PMID 34165914, 2021). "Our study concluded that KDM6B was lowly expressed in breast cancer tissues and correlated with the poor prognosis of patients with breast cancer." (PMID 34165914, 2021). "These transcription factors have been described to be essential for the maintenance of the stem-like phenotype, suggesting that KDM6B regulated stemness properties of breast cancer cells." (PMID 34991274, 2018). "Overexpression of KDM6B has also been shown to promote invasion-metastasis cascades and induce the expression of mesenchymal genes in breast cancer." (PMID 28947976, 2017). "In addition to its apparent oncogenicity, KDM6B has been demonstrated to act as a tumour suppressor, suggesting a context-dependent role for KDM6B in the pathogenesis of breast cancer." (PMID 35915507, 2022). "However, a high KDM6B expression was correlated with a poor DMFS prognosis (p = 0.0075) for breast cancer." (PMID 35783266, 2022). "With the KM survival analyses, we revealed that an irregular KDM6B expression may serve as a prognostic biomarker in several cancers, such as breast cancer, lung cancer, and gastric cancer." (PMID 35783266, 2022). "In addition, KDM6B overexpression repressed proliferation, invasion, migration of breast cancer cells in vitro and metastasis in vivo." (PMID 34165914, 2021). "Moreover, KDM6B down‐regulated the expression of β‐catenin and its accumulation in the nucleus of breast cancer cells." (PMID 34165914, 2021). "KDM6B could inhibit the growth and metastasis of breast cancer by suppressing β‐catenin expression and its nuclear accumulation." (PMID 34165914, 2021). "In addition, we found that the expression of KDM6B in breast cancer tissues was negatively correlated with that of β‐catenin, and overexpression of KDM6B decreased the expression of β‐catenin and its accumulation in the nucleus of breast cancer cells." (PMID 34165914, 2021). "Furthermore, overexpression of KDM6B remarkably inhibited cell proliferation, invasion, migration and epithelial–mesenchymal transition markers of breast cancer cells in vitro and tumor growth and lung metastasis in vivo." (PMID 34165914, 2021). "Moreover, we found the inhibitory role of KDM6B in cell proliferation, invasion and migration in vitro, suggesting a suppressive role of KDM6B in tumor growth and metastasis of breast cancer." (PMID 34165914, 2021). "The results confirmed that the expression of KDM6B decreased in human breast cancer tissues." (PMID 34165914, 2021). "To investigate whether KDM6B is involved in the regulation of migration and invasion of breast cancer cells, we initially performed wound healing assays." (PMID 34165914, 2021). "Furthermore, the expression of KDM6B was significantly lower in patients with breast cancer compared with normal controls (TCGA dataset)." (PMID 34093857, 2021). "Recently, a study about exosomal miRNA in breast cancer suggested that the transmission of miR-138-5p via exosomes could led to downregulation of KDM6B expression, inhibition of M1 polarization and stimulation of M2 polarization." (PMID 34659224, 2021).
breast carcinoma (continued). "Furthermore, overexpression of KDM6B decreased the expression of β‐catenin and its accumulation in the nucleus of breast cancer cells." (PMID 34165914, 2021). "Moreover, breast cancer cell-derived EVs carrying miR-138-5p suppress M1 polarization and upgrade M2 polarization through the inhibition of epigenetic factor lysine demethylase 6B (KDM6B) expression in a suspension coculture system comprising breast cancer cells and macrophages." (PMID 36405712, 2022). "Furthermore, overexpression of KDM6B inhibited the proliferation, migration and metastasis of breast cancer, which might be mediated by regulating the Wnt/β‐catenin signaling pathway." (PMID 34165914, 2021). "Notably, the expression of KDM6B in breast cancer tissues was negatively correlated with that of β‐catenin, and overexpression of KDM6B decreased the expression of β‐catenin and its accumulation in the nucleus of breast cancer cells." (PMID 34165914, 2021). "Taken together, these results indicate that KDM6B may play a suppressing role in breast cancer." (PMID 34165914, 2021). "Therefore, we next examined whether KDM6B regulates the metastasis of breast cancer via Wnt/β‐catenin signaling." (PMID 34165914, 2021). "The results showed a relevance between a low KDM6B expression and poor RFS (p = 0.0012) prognosis for breast cancer." (PMID 35783266, 2022). "Conditioned medium (CM) derived from MDA-MB-231 suppressed KDM6B expression in THP-1 cells, suggesting that a factor secreted from the breast cancer cells was responsible for this effect." (PMID 34093857, 2021). "Similarly, KDM6B has also been associated with the direct activation of the EMT-TF gene SNAI1, or SNAI2, in different cancer models (breast cancer cells, hepatocarcinoma cells, and CRCCs) but KDM6B might also be recruited on specific promoters involved in downstream EMT signaling." (PMID 33291363, 2020). "Knockdown of KDM6B inhibited EMT induced by TGF-β, inhibiting breast cancer cell invasion." (PMID 36233212, 2022). "Inoculation of breast fat pads in mice with KDM6B-overexpressing MDA-MB-231 cells resulted in smaller tumours and fewer metastatic lung nodules, supporting a tumour suppressor role for KDM6B in the growth and metastasis of breast cancer in vivo." (PMID 35915507, 2022). "Furthermore, overexpression of KDM6B remarkably inhibited cell proliferation, invasion, migration and EMT markers of breast cancer cells in vitro and lung metastasis in vivo." (PMID 34165914, 2021). "KDM6B also promotes TGF-β-induced EMT and invasiveness in breast cancer." (PMID 31036064, 2019). "KDM6B regulates the differentiation of cancer stem cells via activating distinct target genes, and may contribute to the pathogenesis of T-ALL, acute myeloid leukemia, breast cancer, Hodgkin’s Lymphoma and Glioblastoma." (PMID 34950587, 2021). "To determine whether miR-138-5p mediated the inhibitory effect of MDA-MB-231 cells on KDM6B expression in macrophages, we first measured miR-138-5p levels in phenotypically distinct breast cancer cell lines, as well as in the nontumorigenic cell line MCF10A." (PMID 34093857, 2021).